BRAF (B-Raf proto-oncogene, serine/threonine kinase)
Diseases named in the same sentence as BRAF in open-access papers (continued):
Sharing a sentence is not in itself a finding about the gene and the disease.
metastatic melanoma (continued). "Mutations in the BRAF oncogene are of increasing relevance in clinical oncology, especially after the approval of the anti-BRAF molecules in the therapy of BRAF positive metastatic melanomas." (PMID 28039443, 2017). "Despite proven efficacy of BRAF inhibitors in BRAFV600 mutation-positive metastatic melanoma, responses remain temporary." (PMID 28915798, 2017). "More recently, the Food and Drug Administration in the United States and European Medicines Agency have approved vemurafenib plus cobimetinib as a combination therapy for patients with BRAF V600E or V600K mutation-positive unresectable or metastatic melanoma." (PMID 28052762, 2017). "These drugs have been approved in many countries for the treatment of patients with unresectable or metastatic melanoma with a BRAF mutation." (PMID 28743309, 2017). "These improved overall and progression-free survival have led to approval of vemurafenib by the Food and Drug Administration (FDA) on August 17, 2011, as a first line treatment in patients with BRAF-mutated unresectable or metastatic melanoma." (PMID 28915798, 2017). "The 2015 United States and European guidelines recommend the use of dabrafenib plus trametinib for metastatic melanoma patients with a BRAF V600 mutation." (PMID 28052762, 2017). "We investigated the regulation of PHB1 by miR-195 and its possible impact on chemoresistance of metastatic melanoma cell lines harboring a BRAF-V600E mutation." (PMID 29126391, 2017). "In the COMBI-v study 704 patients with BRAF mutated metastatic melanoma were randomly assigned to receive either a combination of dabrafenib plus trametinib or vemurafenib alone as a monotherapy." (PMID 28915798, 2017). "A majority of patients with BRAF-mutated metastatic melanoma respond to therapy with BRAF inhibitors (BRAFi), but relapses are common owing to acquired resistance." (PMID 29048432, 2017). "A BRAFi, vemurafenib, and a MEKi, pimasertib, currently used in the treatment of BRAF-mutated metastatic melanoma were evaluated in this way." (PMID 26909610, 2016). "The use of BRAF inhibitors in metastatic melanoma with BRAF mutation ensures clinical improvement of the disease." (PMID 27042173, 2016). "For instance, cutaneous skin melanoma cells bearing BRAFV 600E mutation that respond positively to Vemurafenib, the first BRAF kinase inhibitor approved to treat metastatic melanoma, progress to resistant cells." (PMID 27746730, 2016). "BRAF kinase inhibitors such as Vemurafenib have shown improvement in overall survival, progression-free survival, and response rates in patients with metastatic melanoma with BRAF V600K mutation." (PMID 26989536, 2016). "On this basis, for pts with metastatic melanoma harboring BRAF V600 mutation, a compassionate use program with Dabrafenib first and Dabrafenib and Trametinib later were started." (PMID 26981153, 2016). "Recently presented data also demonstrated that the addition of cobimetinib to vemurafenib was associated with a significant improvement in PFS among patients with BRAF V600 mutated metastatic melanoma." (PMID 26784231, 2016). "The association of dabrafenib with an anti-MEK therapy i. e. trametinib, also showed a significantly higher overall survival than vemurafenib alone in BRAF mutated patients with metastatic melanoma." (PMID 27111917, 2016). "This is the first reported case of complete remission of metastatic melanoma on a BRAF inhibitor (Vemurafenib) in a patient with BRAF V600K mutation to the best of our knowledge." (PMID 26989536, 2016). "Constitutively activating mutations in BRAF are found in a large proportion of metastatic melanomas." (PMID 27448964, 2016). "Inhibitors of mutant BRAF are emerging as standard of care in patients with metastatic melanoma who carry relevant oncogenic mutations." (PMID 27141983, 2016). "Most of the assays for the routine detection of BRAF mutations in metastatic melanomas are PCR-based, but sequencing or immunohistochemistry assays are also widely used." (PMID 27111917, 2016).
metastatic melanoma (continued). "Recent successes include the approval of Zelboraf (Vemurafenib) as a monotherapy alongside a companion genetic test for BRAF mutations for the treatment of adult patients with BRAF V600E mutation-positive unresectable or metastatic melanoma." (PMID 26774505, 2016). "Concurrent administration of VEM and IPI was evaluated in a phase I study of patients with BRAF-mutated metastatic melanoma." (PMID 27532019, 2016). "In this study of 162 patients with BRAF V600 mutated metastatic melanoma, the combination of dabrafenib and trametinib at 2 mg had an improved median PFS at 9.4 months, compared with 5.8 months in the dabrafenib monotherapy group." (PMID 26784231, 2016). "Nivolumab is approved in the United States for the treatment of unresectable or metastatic melanoma as a single agent in patients with disease progression following ipilimumab (Yervoy) and, if positive for BRAF V600 mutation, a BRAF inhibitor." (PMID 28090370, 2016). "Vemurafenib and dabrafenib are potent inhibitors of the kinase domain in mutant BRAF, approved for the treatment of metastatic melanoma with a V600E BRAF mutation." (PMID 27974909, 2016). "Clinical trials of Vemurafenib have shown a therapeutic effect in more than 50% of patients with BRAF V600 mutated metastatic melanomas." (PMID 26828592, 2016). "Vemurafenib (Zelboraf) has demonstrated efficacy in treating metastatic melanoma with a known mutation in BRAF protein." (PMID 26989536, 2016). "The selective BRAF inhibitors vemurafenib and dabrafenib are systemic treatments in patients with metastatic melanoma harbouring a V600 BRAF mutation, which accounts for roughly half cutaneous melanoma." (PMID 26414886, 2016). "The CYP171A1 inhibitor abiraterone, which blocks androgen synthesis, was approved for advanced-stage prostate cancer, and the BRAF inhibitor vemurafenib was approved for metastatic melanoma with the BRAF V600E mutation." (PMID 26751490, 2016). "Histology showed 3 out of 29 lymph nodes positive for metastatic melanoma and mutation testing revealed presence of BRAF V600K mutation." (PMID 26989536, 2016). "This is the first reported case of complete radiological response to a BRAF inhibitor in metastatic melanoma with BRAF V600K mutation and remains disease free even after discontinuation of treatment." (PMID 26989536, 2016). "This phase II, single-arm, open-label study showed that VEM (960 mg twice daily for 6 weeks) followed by IPI 10 mg/kg can be administered safely in patients with previously untreated BRAF-mutated metastatic melanoma." (PMID 27532019, 2016). "Trametinib, a selective inhibitor of mitogen‐activated protein kinase kinase 1 (MEK1) and MEK2, significantly improves progression‐free survival compared with chemotherapy in patients with BRAF V600E/K mutation–positive advanced or metastatic melanoma (MM)." (PMID 27172483, 2016). "At the time our experiments were planned and finalized, the BRAF inhibitor Vemurafenib was the only FDA approved targeted treatment for patients with metastatic melanoma harboring the BRAF mutation." (PMID 27169980, 2016). "In this review, the common cutaneous side effects of BRAF inhibitors in the treatment of metastatic melanoma with BRAF V600E mutation were reviewed." (PMID 27042173, 2016). "The detection of BRAFV600 mutations in patients with metastatic melanoma is important because of the availability of BRAF inhibitor therapy." (PMID 26498143, 2015). "The ‘acquired resistance’ occurring in the tumors that were earlier sensitive to BRAF inhibitor treatment has emerged as a major obstacle in the treatment of the patients with late stage metastatic melanoma with BRAFV600E mutation leading to poor prognosis." (PMID 26497853, 2015). "Patients with metastatic melanoma bearing V600 mutations in BRAF oncogene clinically benefit from the treatment with BRAF inhibitors alone or in combination with MEK inhibitors." (PMID 26208478, 2015).
metastatic melanoma (continued). "We report on a 57-year-old woman suffering from metastatic malignant melanoma positive for BRAF-V600E mutation who developed an acute onset of neurological symptoms." (PMID 26187589, 2015). "The BRIM-3 study was a phase III randomized clinical trial comparing vemurafenib with dacarbazine in 675 treatment-naive patients with BRAF V600E-mutated stage IIIC/IV metastatic melanoma." (PMID 26705496, 2015). "Vemurafenib was granted Marketing Authorization (MA) in Europe in February 2012 for the treatment of adult patients with BRAF V600 mutation-positive unresectable or metastatic melanoma." (PMID 25789737, 2015). "In 2013, the combination of BRAF inhibitor, dabrafenib, and MEKinhibitor, trametinib, was approved for BRAF mutation positive metastatic melanoma patients." (PMID 27508107, 2015). "Small molecules that inhibit V600 mutated BRAF protein, such as vemurafenib and dabrafenib, are effective in treatment of metastatic melanoma." (PMID 25810704, 2015). "Although selective BRAF inhibitors have demonstrated a significant clinical activity in patients with metastatic melanoma harboring a BRAF mutation, the clinical benefit of BRAF inhibitor-based therapy in leptomeningeal disease is not clear." (PMID 25962795, 2015). "Vemurafenib is indicated as an option for first-line therapy in patients with unresectable or metastatic melanoma with BRAF V600E mutation." (PMID 26705496, 2015). "Two previous cases of the development of Dupuytren’s contractures were reported in association with BRAF inhibitor treatment for BRAF V600E mutation-positive metastatic melanoma and metastatic papillary thyroid carcinoma." (PMID 26152183, 2015). "In the United States it was approved by the FDA in 2013 as a single-agent treatment for unresectable or metastatic melanoma with BRAF V600E mutation." (PMID 26171394, 2015). "On the basis of this trial, on January 2014, FDA approved the combination of trametinib and dabrafenib to treat patients with unresectable or metastatic melanoma with BRAF V600E or V600K mutation." (PMID 26171394, 2015). "The determination of NRAS and BRAF mutation status is a major requirement in the treatment of patients with metastatic melanoma." (PMID 26204954, 2015). "In the last years, the treatment of V600 BRAF mutated metastatic melanoma patients has radically changed." (PMID 25810704, 2015). "Supporting these results, loss of RHOB expression in metastatic melanoma tissues is associated with an increased progression-free survival of BRAF-mutant patients treated with vemurafenib." (PMID 26098773, 2015). "Subsequently, vemurafenib, a BRAF inhibitor, was approved in the same year for patients with metastatic melanoma harboring BRAF mutation." (PMID 27508107, 2015). "Phase II trial (BRIM-2) enrolled 132 patients with BRAF V600 mutation previously treated for metastatic melanoma." (PMID 26171394, 2015). "We here describe the clinical course of a V600E BRAF mutated metastatic melanoma patient with systemic disease, who developed tumor progression on superficial soft-tissue metastases during treatment with dabrafenib." (PMID 25810704, 2015). "Vemurafenib, the first agent to target mutated BRAF, is an option for the treatment of advanced or metastatic melanoma based on favorable results from the BRIM-3 trial." (PMID 26705496, 2015). "As BRAF inhibition became the reference treatment of BRAFV600-mutant metastatic melanomas, screening for BRAFV600 mutations was a major requirement for an optimal treatment with targeted therapies." (PMID 26204954, 2015). "It is approved for the treatment of BRAF V600 mutation-positive unresectable or metastatic melanoma." (PMID 26187589, 2015). "Vemurafenib is approved for the treatment of metastatic melanoma in patients with BRAF V600 mutation." (PMID 25789737, 2015). "In phase I (BRIM-1) patients with advanced tumors, the majority of whom had metastatic melanoma with BRAF V600E mutation (89%), underwent treatment with vemurafenib." (PMID 26171394, 2015).
metastatic melanoma (continued). "V600BRAF mutations drive approximately 50% of metastatic melanoma which can be therapeutically targeted by BRAF inhibitors (BRAFi) and, based on resistance mechanisms, the combination of BRAF and MEK inhibitors (BRAFi + MEKi)." (PMID 26139106, 2015). "A multicenter phase II trial of vemurafenib in patients with previously treated metastatic melanoma with BRAF V600 mutation was designed with the primary endpoint of overall response rate and a secondary endpoint of overall survival." (PMID 26705496, 2015). "In the phase 3 trial in 322 patients who had metastatic melanoma with V600E or V600K BRAF mutation, trametinib improved progression-free survival and overall survival times in comparesion with dacarbazine or paclitaxel." (PMID 25915534, 2015). "Patients with metastatic melanoma carrying a BRAF mutation at the V600 position (confirmed by DNA sequencing) who received treatment with BRAFi (n = 32) were included in this study." (PMID 24733413, 2014). "About 80% of patients with BRAF-mutated metastatic melanoma treated with BRAF inhibitors display tumor regression with a partial response in approximately 50% of patients." (PMID 25501056, 2014). "BRAF inhibitors vemurafenib and dabrafenib achieved improved overall survival over chemotherapy and have been approved for the treatment of BRAF-mutated metastatic melanoma." (PMID 25344914, 2014). "The novel MEK inihibitor trametinib, which we discovered by screening to detect p15-inducing agents, improved progression-free and overall survival in patients with BRAF V600E-mutated metastatic melanoma, and was approved by FDA in 2013." (PMID 25422890, 2014). "Although there is very little experience using vemurafenib in children, it has shown significant activity against BRAF V600E mutation-positive metastatic melanoma in adults." (PMID 25563358, 2014). "BREAK-MB was a multicenter open-label phase II trial that enrolled patients with BRAF V600E- orV600K-mutated metastatic melanoma and brain metastases." (PMID 25089220, 2014). "Here, we report the case of a patient with metastatic melanoma harboring a rare and complex BRAF mutation." (PMID 25265970, 2014). "In 2011, two agents, ipilimumab (a fully human monoclonal antibody that blocks CTLA-4 to promote antitumor immunity) and vemurafenib (a potent inhibitor of mutated V600E BRAF) were approved in Europe and the US for the treatment of metastatic melanoma." (PMID 25502446, 2014). "Dabrafenib is also FDA-approved as a combination therapy with trametinib for the treatment of patients with unresectable or metastatic melanoma with a BRAF V600E/K mutation." (PMID 25037456, 2014). "Vemurafenib (Zelboraf) and dabrafenib (Tafinlar) are specific BRAF V600 inhibitors recently approved by the US FDA as single agent treatments for unresectable or metastatic melanoma in patients with the BRAF V600 mutation." (PMID 25037456, 2014). "The addition of cobimetinib to vemurafenib was associated with a significant improvement in PFS among patients with BRAF V600-mutated metastatic melanoma, at the cost of some increase in toxicity." (PMID 25374620, 2014). "Twenty-three patients with BRAF mutated metastatic melanoma were enrolled in the protocol with BRAF inhibitors for compassionate use at the University of Modena." (PMID 24591764, 2014). "Dabrafenib is a specific BRAF V600 inhibitor (BRAFi) approved by the US FDA as a single agent treatment for unresectable or metastatic melanoma in patients with the BRAF V600E mutation as detected by an FDA-approved test." (PMID 25037456, 2014). "Almost 50% of metastatic melanoma patients harbor a BRAFV600 mutation andthe introduction of BRAF inhibitors has improved their treatment options." (PMID 25344914, 2014). "An ongoing targeted and immunotherapy trial utilizes dabrafenib with or without trametinib combined with ipilimumab in patients with BRAF V600E/K-mutated metastatic melanoma (NCT01767454)." (PMID 25610709, 2014).
metastatic melanoma (continued). "For example, in this Baylor panel BRAF mutations are targeted, where treatment with vemurafenib and dabrafenib has demonstrated BRAF Val600-specific metastatic melanoma antitumor activity." (PMID 24917882, 2014). "In various prospective studies, vemurafenib has demonstrated significant clinical benefits in patient with p.V600E BRAF-mutation-positive metastatic melanoma." (PMID 25265970, 2014). "Dr Robert concluded that a combination of dabrafenib and trametinib, as compared with dabrafenib alone, improved the rate of PFS in previously untreated patients who had metastatic melanoma with BRAF V600E or V600K mutations." (PMID 25374620, 2014). "Randomized trials have shown that metastatic melanoma patients with BRAF mutation benefit from treatment with selective BRAF inhibitors—vemurafenib (Zelboraf; Roche, Basel, Switzerland) and dabrafenib (Tafinlar; GlaxoSmithKline, Research Triangle Park, NC)." (PMID 25501056, 2014). "It has clinical activity with a manageable safety profile in phase 1 and 2 clinical trials, in patients with BRAF(V600)-mutated metastatic melanoma." (PMID 24455677, 2013). "In a phase III randomized trial of vemurafenib versus DTIC in 675 patients with BRAF V600E mutated previously untreated metastatic melanoma patients, overall survival was 84% for vemurafenib group and 64% for DTIC group at 6-month analysis." (PMID 24499550, 2013). "In summary, we describe the first report of metastatic melanoma of the esophagus arising in a background of BE with molecular analysis for the presence of BRAF and KIT mutations." (PMID 24220097, 2013). "The BRAF inhibitor vemurafenib (PLX4032) improves survival among patients with metastatic melanoma, and suppresses growth of BRAF-mutated human ATC in a mouse model." (PMID 24267151, 2013). "Trametinib is being evaluated by FDA for the treatment of metastatic melanoma with BRAF V600 mutation." (PMID 23587417, 2013). "Vemurafenib, an inhibitor of genetically activated BRAF, is now commonly prescribed for metastatic melanoma harboring a BRAF mutation." (PMID 24289205, 2013). "We have analysed the NRAS and BRAF mutational status of a series of 44 early passage lines developed from New Zealand patients with metastatic melanoma." (PMID 23658559, 2013). "BRAF inhibitors have demonstrated improvement of overall survival in patients with metastatic melanoma and BRAFV600 mutations." (PMID 23976959, 2013). "Taking all advantages together, we propose U-BRAFV600 approach as a universal diagnostic tool in the automated evaluation of metastatic melanoma and other tumors for their BRAF mutation state prior to targeted therapy." (PMID 23555633, 2013). "Immunohistochemical (IHC) detection of BRAF V600E with a mutation specific antibody (clone VE1) was first described in metastatic melanoma and papillary thyroid carcinoma, and the antibody is currently commercially available." (PMID 24298448, 2013). "A multicenter, phase II study (BRIM-2) evaluated vemurafenib in patients who had BRAF V600E mutation—positive metastatic melanoma." (PMID 24455362, 2013). "Vemurafenib was subsequently FDA-approved for the treatment of BRAF V600E-mutated metastatic melanoma." (PMID 23717811, 2013). "This combination is now being tested in a phase III trial versus vemurafenib in BRAF-mutated patients with metastatic melanoma (NCT01400451)." (PMID 23402397, 2013). "Vemurafenib acts as a potent inhibitor of BRAF-mediated cell signaling and proliferation, and has produced improved progression-free and overall survival in previously untreated metastatic melanoma containing BRAF V600E and V600K mutations." (PMID 24314265, 2013). "For instance, vemurafenib is the first B-RAF inhibitor that received FDA approval in 2011 for the treatment of BRAF V600E/K mutation positive metastatic melanoma." (PMID 23587417, 2013).